PSMB5 (proteasome 20S subunit beta 5)
Description:
Component of the 20S core proteasome complex involved in the proteolytic degradation of most intracellular proteins. This complex plays numerous essential roles within the cell by associating with different regulatory particles. Associated with two 19S regulatory particles, forms the 26S proteasome and thus participates in the ATP-dependent degradation of ubiquitinated proteins. The 26S proteasome plays a key role in the maintenance of protein homeostasis by removing misfolded or damaged proteins that could impair cellular functions, and by removing proteins whose functions are no longer required. Associated with the PA200 or PA28, the 20S proteasome mediates ubiquitin-independent protein degradation. This type of proteolysis is required in several pathways including spermatogenesis (20S-PA200 complex) or generation of a subset of MHC class I-presented antigenic peptides (20S-PA28 complex). Within the 20S core complex, PSMB5 displays a chymotrypsin-like activity.
Synonyms: LMPX; MB1
Tractability: Small molecule: an approved drug acts on it; a structure with a bound ligand is known; a high-quality ligand is known; it belongs to a druggable protein family. PROTAC: ubiquitination databases record sites on it; its protein half-life has been measured; a small molecule that binds it is known. Other modalities: an approved drug acts on it.
Target class: Threonine protease; Protease; Threonine protease T1A subfamily; Threonine protease PBT clan; Enzyme
Chemical probes: Cbz-Glu(OtBu)-Ala-LeuVSMe, Cbz-Ile-Leu-Ala-LeuVSMe, Cbz-Ile-hPhe-Ala-LeuVSMe, Epoxomicin, PD081684, PD081859, PD082003, PD082208, PD082299, PD082664, PD082761, PD082857, PD083250, PD083761, PD084046, PD084547, PD084658, PD084899, PD084905, PD085062, and 26 more
Gene: Protein-coding gene on chromosome 14 (23,016,543 to 23,035,230, reverse strand). Ensembl gene ENSG00000100804.
Subcellular location: Cytoplasm; Nucleus
Subcellular location (Human Protein Atlas): Nucleoplasm; Centrosome; Mid piece; Principal piece
Pathways (Reactome):
Immune System: AMPK-induced ERAD and lysosome mediated degradation of PD-L1(CD274); Activation of NF-kappaB in B cells; Antigen processing: Ub, ATP-independent proteasomal degradation; Antigen processing: Ubiquitination & Proteasome degradation; CLEC7A (Dectin-1) signaling; Cross-presentation of soluble exogenous antigens (endosomes); Dectin-1 mediated noncanonical NF-kB signaling; Downstream TCR signaling; ER-Phagosome pathway; FCERI mediated NF-kB activation; GSK3B-mediated proteasomal degradation of PD-L1(CD274); Interleukin-1 signaling; NIK-->noncanonical NF-kB signaling; SPOP-mediated proteasomal degradation of PD-L1(CD274); TNFR2 non-canonical NF-kB pathway
Cell Cycle: APC/C:Cdc20 mediated degradation of Securin; APC/C:Cdh1 mediated degradation of Cdc20 and other APC/C:Cdh1 targeted proteins in late mitosis/early G1; Autodegradation of Cdh1 by Cdh1:APC/C; Autodegradation of the E3 ubiquitin ligase COP1; Cdc20:Phospho-APC/C mediated degradation of Cyclin A; FBXL7 down-regulates AURKA during mitotic entry and in early mitosis; G2/M Checkpoints; SCF(Skp2)-mediated degradation of p27/p21; SCF-beta-TrCP mediated degradation of Emi1; Separation of Sister Chromatids; The role of GTSE1 in G2/M progression after G2 checkpoint; Ubiquitin-Mediated Degradation of Phosphorylated Cdc25A; Ubiquitin-dependent degradation of Cyclin D
Signal Transduction: Asymmetric localization of PCP proteins; Degradation of AXIN; Degradation of DVL; Degradation of GLI1 by the proteasome; Degradation of GLI2 by the proteasome; Degradation of beta-catenin by the destruction complex; GLI3 is processed to GLI3R by the proteasome; Hedgehog 'on' state; Hedgehog ligand biogenesis; MAPK6/MAPK4 signaling; Negative regulation of NOTCH4 signaling; Regulation of PTEN stability and activity
and 28 more pathways
Gene Ontology:
Molecular function: peptidase activity; protein binding; threonine-type endopeptidase activity; endopeptidase activity
Biological process: proteasomal protein catabolic process; proteasome-mediated ubiquitin-dependent protein catabolic process; proteolysis; regulation of proteasomal protein catabolic process; response to oxidative stress; apoptotic process; cellular response to type I interferon; DNA damage response; DNA repair; flagellated sperm motility; meiotic cell cycle; proteasomal ubiquitin-independent protein catabolic process; proteasome assembly; regulation of G1/S transition of mitotic cell cycle; spermatogenesis; protein catabolic process
Cellular component: cytoplasm; extracellular exosome; nucleoplasm; nucleus; proteasome complex; proteasome core complex; cytosol; proteasome core complex, beta-subunit complex; proteasome storage granule; spermatoproteasome complex; synaptic vesicle
Genetic constraint (gnomAD): Loss-of-function variants: 2 observed, 24.67 expected, observed/expected ratio (o/e) 0.0811, 90% interval 0.032 to 0.25. The upper end of that interval is the gene's LOEUF score, 0.25, which puts it in group 1 of 6, group 1 being the genes least tolerant of losing a copy. Missense variants: 269 observed, 365.52 expected, observed/expected ratio (o/e) 0.74, 90% interval 0.67 to 0.81. Synonymous variants: 133 observed, 144.24 expected, observed/expected ratio (o/e) 0.92, 90% interval 0.8 to 1.07.
Homologues: Orthologues: chimpanzee PSMB5 (100% identical), macaque PSMB5 (99% identical), rabbit PSMB5 (98% identical), dog PSMB5 (96% identical), guinea pig PSMB5 (96% identical), mouse Psmb5 (94% identical), rat Psmb5 (94% identical), tropical clawed frog psmb5 (76% identical), zebrafish psmb5 (71% identical), Drosophila melanogaster Prosbeta1 (20% identical), Caenorhabditis elegans pbs-1 (20% identical). Paralogues in human: PSMB8 (59% identical), PSMB11 (45% identical), PSMB6 (26% identical), PSMB9 (22% identical), PSMB7 (21% identical), PSMB10 (21% identical), PSMA2 (20% identical), PSMB1 (18% identical), PSMB4 (18% identical), PSMA4 (18% identical), PSMB3 (18% identical), PSMA1 (16% identical), and 6 more.
Diseases named in the same sentence as PSMB5 in open-access papers:
PSMB5 is named in the same sentence as 178 diseases in open-access papers, as found by Europe PMC text mining. Sharing a sentence is not in itself a finding about the gene and the disease. The quoted sentences say what the papers report.
multiple myeloma (23 papers, 2013 to 2025). "Further, resistance to the targeted proteasome inhibitor bortezomib in multiple myeloma is conferred by a missense mutation in PSMB5 near the drug-binding pocket." (PMID 41502952, 2025). "Overexpression and mutations of PSMB5 have been reported to contribute to drug resistance to proteasome inhibitors in several malignancies, such as multiple myeloma, breast cancer, and prostate cancer 66-68." (PMID 35693739, 2022). "Several other studies showed an association between overexpression of PSMB5 and drug resistance in T-lymphoblastic lymphoma, myeloma, and gastric cancer." (PMID 36293493, 2022). "Resistance to bortezomib is common in relapsed multiple myeloma patients and can be caused by point mutations in the bortezomib binding site of PSMB5 or by PSMB5 overexpression." (PMID 29515774, 2018). "Recently, M3258 was synthesized using the α-aminoboronic acid scaffold as a starting point to optimize selectivity for PSMB8 (> 500fold over PSMB5) and has entered early clinical trials for multiple myeloma." (PMID 38049829, 2023). "TIR-199 also effectively inhibits the proteasome in primary myeloma cells of patients, and bypasses the PSMB5 A49T+A50V bortezomib-resistant mutant." (PMID 35088066, 2022). "Ixazomib citrate, originally used in combination treatment with Lenalidomide and Dexamethasone to treat multiple myeloma, can be repurposed against PSMB5 dysregulation." (PMID 36293493, 2022). "Although the roles of PSMC gene mutations in cancer remain unstudied, multiple mutations in other proteasome family genes, i.e., PSMB5, PSMB6, and PSMB7, are associated with the myeloma cell survival." (PMID 35938038, 2022). "Bortezomib was approved by the Food and Drug Administration (FDA) for multiple myeloma or mantle cell lymphoma, which targets PSMB5 in 20S core particles." (PMID 33154524, 2020). "In particular, increased PSMB5 mRNA expression was found in a myeloma patient who subsequently developed bortezomib resistance." (PMID 27599459, 2016). "Upregulated expression of the PSMB5 gene was confirmed in bone marrow cells of multiple myeloma patients who developed BTZ resistance." (PMID 24608798, 2014). "We also found upregulated expression of the PSMB5 gene contributed to drug resistance in patient with multiple myeloma when treated with bortezomib-based regimen." (PMID 24252210, 2013). "Bortezomib-resistance in myeloma occurs either due to up-regulation of HSF1 activity or due to altered redox homeostasis or, in rare cases, due to accumulation of mutations in key bortezomib-docking sites in proteasome subunit of PSMB5." (PMID 36622366, 2023). "For example, bortezomib, a selective inhibitor of the β5 subunit of the proteasome (PSMB5), has exhibited significant success in the treatment of patients with multiple myeloma and diffuse large B-cell lymphoma, probably because of the high secretory activity of these cells." (PMID 36139473, 2022). "Mutations and overexpression of the PSMB5 (β5) gene were observed in vitro in BTZ-adapted myeloma cell lines, but never in vivo in MM patients refractory to BTZ." (PMID 32039016, 2019). "Previous studies have found mutations in the proteasome subunit PSMB5 (β5) in long-term BTZ-adapted myeloma cell lines, but not in patients refractory to BTZ." (PMID 32039016, 2019). "Bortezomib, a peptide boronic acid congener, directly inhibits the chymotrypsin‐like activity of the proteasome PSMB5 subunit and is used for the treatment of multiple myeloma; it is also undergoing clinical trials for the treatment of several epithelial cancers." (PMID 26639105, 2016). "Acquired resistance to proteasome inhibition has been correlated in cellular models with UPP upregulation and/or mutations of the PSMB5 gene; yet, no mutations have been found in the PSMB5 gene in myeloma patients being refractory to or relapsed from BTZ therapy." (PMID 31320986, 2019).
multiple myeloma (continued). "However, no mutations in PSMB5 have been detected in myeloma patients refractory to, or relapsed from, bortezomib treatment." (PMID 24252210, 2013). "The proteasome inhibitors (PIs) bortezomib and carfilzomib, which target proteasome 20S subunit beta 5 (PSMB5) in cells, are widely used in multiple myeloma (MM) treatment." (PMID 36040812, 2022).
hepatocellular carcinoma (22 papers, 2011 to 2026). A malignant tumor that arises from hepatocytes. "High PSMB5 expression was associated with poor survival in adult hepatocellular carcinoma, highlighting the proteasome as a candidate for therapeutic vulnerability." (PMID 42193875, 2026). "In the present study, we observed that PSMB5 is overexpressed in hepatocellular carcinoma (HCC) tissues and high levels of PSMB5 expression are associated with worse overall survival." (PMID 36062301, 2022). "PSMB5 mRNA overexpression has also been observed in bortezomib-resistant hepatocellular carcinoma (HCC) cell lines (HepG2 and Huh7) treated with stepwise increasing concentrations of bortezomib over ~6 months." (PMID 34308274, 2021). "Functional validation further confirmed that siRNA-mediated knockdown of PSMB5 and PSMB6 significantly impaired proliferation across multiple hepatocellular carcinoma cell lines." (PMID 42280256, 2026).
breast carcinoma (13 papers, 2016 to 2025). "Curcumin suppresses 20S proteasome activity in breast cancer cells by upregulating miR-142-3p and downregulating its target, such as the proteasome 20S subunit beta 5 (PSMB5)." (PMID 36612314, 2023). "Here, we found four upregulated hub genes (RPSA, SEC61A1, ITGB1, PSMB5) and three downregulated hub genes (PSME3, SNRNP70, SRSF3) that are significantly associated with poor overall survival of breast cancer patients." (PMID 36293493, 2022). "The prognostic significance of PSMB5 is consistent with a previous study that established a link between high PSMB5 expression and enhanced tumor progression in breast cancer." (PMID 36123629, 2022). "PSMB5, part of the proteasome β subunits (PSMB) family and crucial in the ubiquitin-proteasome system, is linked with oncogenic traits and immunosuppression in M2 macrophages; high PSMB5 levels predict poor survival in breast cancer." (PMID 38786019, 2024). "In addition, the tumor‐promoting role of PSMB5 has been reported in relation to many human cancers, such as breast cancer, esophageal squamous cell carcinoma and prostate cancer." (PMID 36062301, 2022). "Furthermore, bioinformatics analysis revealed that up-regulation of PSMB5 was observed in breast cancer tissues and that overexpression of PSMB5 was predictive of worse survival." (PMID 35693739, 2022). "Similar to PSMB5, PSMB7 was found to contribute to anthracycline resistance and was predictive of significantly shorter survival in breast cancer." (PMID 35693739, 2022). "In this context, Deng and colleagues demonstrated that the expression of six proteasome subunits including PSMA1, PSMB5, PSMD1, PSMD2, PSMD8 and PSMD11 was increased over three-fold in breast cancer tissues when compared to adjacent normal tissues." (PMID 27966459, 2017). "PSMB5 is a member of the PSMB family and ubiquitin-proteasome system, which was demonstrated to play important roles in tumor progression and immune cell infiltration, especially in breast cancer." (PMID 35898492, 2022). "Moreover, breast cancer patients with tumors exhibiting the lowest quartile of PSMB2 and PSMB5 combined mRNA expression showed reduced 5-year survival compared to patients with tumors in the highest quartile." (PMID 26930717, 2016).
prostate carcinoma (8 papers, 2010 to 2025). A carcinoma that arises from epithelial cells of the prostate gland. "Low expression of miR - 127 - 3p promotes prostate cancer cell invasion and migration in vitro by targeting the proteasome β subunit PSMB5." (PMID 40837012, 2025). "CTCF transcriptionally represses miR - 127 - 3p by interacting with its promoter, activating the CTCF/miR - 127 - 3p/PSMB5 axis to promote prostate cancer bone metastasis." (PMID 40837012, 2025). "Beside, a recent study showed that PSMB5 was involved in the prostate cancer bone metastasis." (PMID 35693739, 2022).
triple-negative breast carcinoma (7 papers, 2020 to 2024). An invasive breast carcinoma which is negative for expression of estrogen receptor (ER), progesterone receptor (PR), and human epidermal growth factor receptor 2 (HER2). "Increased PSMB5 expression has been associated with a less favorable outcome in triple negative breast cancer (TNBC), while silencing PSMB5 sensitized TNBC cells to chemotherapy." (PMID 36578789, 2022). "Studies have shown that proteasome subunit beta 5 (PSMB5) is overexpressed in triple-negative breast cancer and significantly associated with a poor prognosis 36 and that knockdown of PSMB5 gene expression inhibits MDA-MB-231 cell growth and migration." (PMID 33854621, 2021). "PSMB5 is associated with proliferation and drug resistance in triple-negative breast cancer." (PMID 35379165, 2022). "PSMB5 showed high expression in triple-negative breast cancer patients in addition to immuno-suppressive effects and oncogenic characteristics in several tumors." (PMID 35565454, 2022). "Moreover, in triple-negative breast cancer cells, the expression of proteasomal genes PSMB4 and PSMB5 was dependent on the expression of splice factors PRPF8 and PRPF38A." (PMID 32545483, 2020).
leukemia (5 papers, 2013 to 2021). A malignant (clonal) hematologic disorder, involving hematopoietic stem cells and characterized by the presence of primitive or atypical myeloid or lymphoid cells in the bone marrow and the blood. "Taken together, inhibition of the β5 subunit is essential for the anti-leukemia effect of PIs and PSMB5 mutations emerging after prolonged PI treatment attenuate the inhibitory potency and confer resistance in leukemia cells." (PMID 29071527, 2017). "BTZ-resistance associated with a single point mutation in PSMB5 has been demonstrated by us and others for leukemia cell lines of lymphoid and myeloid origins, as well as solid tumor cell lines." (PMID 23305345, 2013). "We previously showed that bortezomib-resistant human leukemia cell lines expressed significantly lower levels of immunoproteasome at the expense of constitutive proteasomes, which harbored point mutations in exon 2 of the PSMB5 gene encoding the β5 subunit." (PMID 24418325, 2014).
liver cancer (5 papers, 2021 to 2025). An epithelial or non-epithelial malignant neoplasm that arises from the liver. "Here, we reveal that in liver cancer cells, PCBP2 facilitates the TRIB2-induced reduction in global K48-Ub levels by elevating the activity of PSMB5, one of the major components of the proteasome that contains active sites." (PMID 33414446, 2021).
melanoma (4 papers, 2013 to 2024). A malignant, usually aggressive tumor composed of atypical, neoplastic melanocytes. "Moreover, PSMB5 is produced by melanocytes, further accentuating its relevance in the context of melanoma." (PMID 39015503, 2024). "Our results are in strong agreement with existing literature, suggesting that decreased PSMB5 protein expression might serve as a marker for enhanced prognosis in melanoma immunotherapy response." (PMID 39015503, 2024).
viral infection (4 papers, 2023 to 2025). "Notably, PSMB5 elevation was more pronounced in HBV-infected non-tumor livers than in HCC tissues, suggesting that viral infection itself is a stronger driver of proteasome activation than malignant transformation." (PMID 41305476, 2025).
gastric cancer (3 papers, 2022 to 2024). A primary or metastatic malignant neoplasm involving the stomach. "Similar to PSMB5, Proteasome 20S subunit beta 8 (PSMB8) overexpression correlates with the progression of gastric cancer, its inhibition in glioblastoma increases apoptosis and decreases angiogenesis, and its mutation leads to inflammation and lipodystrophy." (PMID 37111759, 2023).
sarcoma (3 papers, 2010 to 2021). A usually aggressive malignant neoplasm of the soft tissue or bone. "Furthermore, survival analysis of sarcomas patients, including liposarcoma patients, revealed that a higher expression of PSMB5 mRNA correlates with a poorer clinical outcome." (PMID 32851475, 2021).
bladder cancer (2 papers, 2022 to 2025). "We obtained the results of immunohistochemical staining of PSMD14, PRPF19, PSMB5, and TPR in normal tissues and bladder cancer tissues and demonstrated that these four genes were highly expressed in tumor tissues and lowly expressed in normal tissues." (PMID 35898492, 2022).
COVID-19 (2 papers, 2022 to 2023). A disease caused by infection with severe acute respiratory syndrome coronavirus 2. "Interestingly, PSMB5, PSMB6, and PSMB7 also did not reveal a significant difference between COVID-19 patients and HC, suggesting an overexpression of the immunoproteasome rather than constitutive proteasome." (PMID 35327634, 2022).
Dystonia (2 papers, 2021 to 2025). An abnormally increased muscular tone that causes fixed abnormal postures. "Here the authors characterise THAP1 as a transcriptional activator of PSMB5, suggesting that proteasome dysfunction might underlie the pathogenesis of THAP1 dystonia." (PMID 39929834, 2025). "First, the identification of THAP1 as a critical activator of PSMB5 expression suggests that proteasome dysfunction could underlie the pathogenesis of DYT-THAP1, although, to the best of our knowledge, no other mutations in proteasome genes have so far been associated with dystonia." (PMID 39929834, 2025). "Finally, leveraging a phenotypic assay to systematically assess the activity of THAP1 mutants at the endogenous PSMB5 locus, we define the transcriptional activity of THAP1 mutants found in dystonia patients." (PMID 39929834, 2025).